PER1 (period circadian regulator 1)
Diseases named in the same sentence as PER1 in open-access papers (continued):
Sharing a sentence is not in itself a finding about the gene and the disease.
Stroke (3 papers, 2024 to 2025). Sudden impairment of blood flow to a part of the brain due to occlusion or rupture of an artery to the brain. "In our study, the observed increases in Per1 and Cry1 expression suggest that these genes may play a key role in mediating the circadian disturbances seen after stroke." (PMID 39957482, 2025). "Moreover, coordinated changes in the co-expression of PER1 and CRY1 suggest that the core clock gene network plays a critical role in post-stroke sleep homeostasis disruption." (PMID 41451215, 2025).
type 2 diabetes (3 papers, 2014 to 2020). "Moreover, expression levels of per2 and cry2 were significantly lower in islets from human donors with type 2 diabetes and mRNA expression levels of per1 and per2 were significantly lower in the leucocytes of patients with type 2 diabetes than in non-diabetic controls." (PMID 24736612, 2014). "Impairment of the circadian clock genes such as CLOCK, BMAL1, cryptochrome (CRY1 and CRY2), and period (PER1, PER2, and PER3) contributes to the decrease in glucose tolerance, defective β-cell function, and the development of type 2 diabetes." (PMID 28352282, 2017). "Additionally, in patients with type 2 diabetes, those with the poorest sleep quality showed a dampened mRNA expression of clock genes such as BMAL1 and PER1." (PMID 32823749, 2020). "In a human study, leucocytes sampled from subjects with type 2 diabetes expressed significantly lower transcript levels of BMAL1, PER1, and PER3 compared with leucocytes from normal controls; moreover, transcript expression was inversely correlated with HbA1c levels." (PMID 28352282, 2017). "On the other hand, mechanisms that impair the circadian clock genes, such as circadian locomotor output cycles kaput (CLOCK), brain and muscle Arnt-like protein 1 (BMAL1), and period genes (PER1, PER2, and PER3), contribute to defective beta-cell function and development of type 2 diabetes." (PMID 28352282, 2017).
acute myeloid leukemia (2 papers, 2021). Acute myeloid leukemia (AML) is a group of neoplasms arising from precursor cells committed to the myeloid cell-line differentiation. "A translocation involving PER1 gene has been described associated to occurrence of acute myeloid leukemia, and the inactivation of the gene has been associated to the pathogenesis of the disease." (PMID 33804124, 2021). "In acute myeloid leukemia (AML), PER2, PER3, and CRY levels are reduced due to reduced expression of CCAAT/enhancer-binding proteins (C/EBPs), while BMAL1, CLOCK, and PER1 levels increase." (PMID 34966277, 2021).
allergic rhinitis (2 papers, 2018 to 2023). Inflammation of the nasal mucous membranes caused by an IgE-mediated response to external allergens. "The present study investigates the expression level and distribution pattern of PER1, PER2, CLOCK, and BMAL1 genes in nasal mucosa of healthy controls, allergic rhinitis patients, and normal rats." (PMID 29534090, 2018).
anaemia (2 papers, 2020 to 2022). "Per1/2‐null hosts tend to experience greater anaemia than WT hosts because mice deficient in Per2 exhibit high susceptibility to acute erythrocyte stressors." (PMID 34778983, 2022). "Specifically, Per1/2‐null TRF hosts experience the most severe anaemia, losing approximately twice as many RBC as WT mismatched hosts, with Per1/2‐null all‐day fed and WT matched hosts experiencing an intermediate loss." (PMID 34778983, 2022). "We also assessed whether anaemia and parasite performance varied between WT and Per1/2-null mice." (PMID 32781954, 2020).
autoimmune disease (2 papers, 2025). A disorder resulting from loss of function or tissue destruction of an organ or multiple organs, arising from humoral or cellular immune responses of the individual to their own tissue constituents. "Briefly, this study highlights that the circadian clock can directly control the immunosuppressing function of Treg through the core‐clock gene Per1‐dependent mitochondrial metabolism in autoimmune disease." (PMID 39823532, 2025).
Cerebral ischemia (2 papers, 2023 to 2025). Restriction of arterial blood supply to the brain associated with insufficient oxygenation to support the metabolic requirements of the tissue. "It is indicated that PER1 deficiency may slow down the autophagic machinery, increasing neuronal susceptibility to cerebral ischemia." (PMID 41451215, 2025). "In a mouse model of cerebral ischemia, KO of PER1 eliminated the circadian variation in infarct volume, abolishing the protective effect observed during the active phase (nighttime)." (PMID 41451215, 2025).
cognitive deficit (2 papers, 2023). "Zebrafish lacking the PER1b gene (an analog of the human PER1 gene) and Per1-KO mice display hyperactive, impulsive-like, and cognitive deficit-like behaviors." (PMID 37606043, 2023). "In addition, as it was a cross-sectional study, we could not explain the causal relationship and specific mechanism between the promoter methylation of PER1, CRY1 and cognitive impairment in CSVD patients." (PMID 37293664, 2023).
cutaneous melanoma (2 papers, 2021 to 2023). A primary melanoma arising from atypical melanocytes in the skin. "According to the cBioPortal and TIMER 2.0 database, the most mutated circadian genes among cutaneous melanoma patients were PER1, PER2, RORB and RORC." (PMID 37373286, 2023).
Dyskinesia (2 papers, 2021 to 2025). A movement disorder which consists of effects including diminished voluntary movements and the presence of involuntary movements. "Genetic analyses revealed significant enrichment of loss-of-function variants (e.g., missense mutations) in the PER1 gene among PD cohorts, which were associated with dyskinesia." (PMID 41451215, 2025). "A whole-exome sequencing study confirmed that PD patients carrying deleterious PER1 variants exhibited a higher incidence of dyskinesia, highlighting these variants as critical risk factors for PD-related motor symptoms." (PMID 41451215, 2025).
esophageal cancer (2 papers, 2016 to 2021). A primary or metastatic malignant neoplasm involving the esophagus. "Since the level of PER2 expression correlates with apoptosis related genes, it will be important to determine whether PER2 oscillatory expression sensitizes esophageal cancer cells to other anti-cancer therapies and whether PER1 is involved in this process." (PMID 33810377, 2021). "The esophageal cancer cells were negatively isolated by MACS and subjected to RT-qPCR to detect the expression of circadian clock molecule mRNA, including NFIL3, Per1, Per2, Bmal1, Cry1, Cry2, Clock and Npas2." (PMID 26898709, 2016).
inflammatory bowel disease (2 papers, 2015 to 2025). A spectrum of small and large bowel inflammatory diseases of unknown etiology. "Circadian clock genes (including PER1) are downregulated in intestinal tissues and peripheral blood mononuclear cells of patients with inflammatory bowel disease (IBD)." (PMID 41451215, 2025). "PER1 regulates immune cell functions, inflammatory factor expression, and signaling pathways, thereby playing a critical role in immune and inflammatory responses, with significant implications particularly in the pathogenesis of inflammatory bowel disease and allergic airway inflammation." (PMID 41451215, 2025).
ischemic stroke (2 papers, 2023 to 2025). A stroke disorder caused by obstruction of blood flow to the brain, due to thrombotic (local blood clot formation) or embolic (due to a blood clot or other material traveling from another site) event. "In a rat model of ischemic stroke, pineal PER1 mRNA and protein levels were significantly elevated, particularly in aged rats, which correlated with sleep-wake cycle disturbances, increased cortisol levels, and decreased melatonin secretion." (PMID 41451215, 2025).
memory impairment (2 papers, 2018 to 2023). "Finally, to determine whether overexpression of Per1 in the dorsal hippocampus is sufficient to ameliorate age-related memory impairments, we locally upregulated Per1 using two complementary methods." (PMID 30127461, 2018).
nasopharyngeal carcinoma (2 papers, 2024 to 2025). A carcinoma arising from the nasopharyngeal epithelium. "Additionally, PER1 overexpression reduces invasion and migration of nasopharyngeal carcinoma cells." (PMID 41451215, 2025). "Similarly, tissue expression of chronobiological markers like PER1 was found to be inversely correlated with ferroptosis markers like GPX4 in human nasopharyngeal carcinoma (NPC) cell line (CNE2) and NPC tissues." (PMID 39199335, 2024).
osteoarthritis (2 papers, 2018 to 2025). A noninflammatory degenerative joint disease occurring chiefly in older persons, characterized by degeneration of the articular cartilage, hypertrophy of bone at the margins and changes in the synovial membrane. "The expression levels of BMAL1 and PER1 are normally in antiphase with each other, as demonstrated, for example, in the synovial membrane samples obtained from patients with osteoarthritis, where high BMAL1 expression coexisted with low PER1 expression." (PMID 29534090, 2018).
ovarian serous tumor (2 papers, 2021 to 2023). A benign, borderline, or malignant epithelial tumor of the ovary characterized by the presence of neoplastic epithelial cells that, in well differentiated tumors, resemble the epithelial cells of the fallopian tube and, in poorly differentiated tumors, show anaplastic features. "The validation experiments showed that the mRNA of PER1, AKAP12, and MMP17 was highly expressed in normal ovarian epithelial cells compared to SOC cell lines and there was a positive correlation between protein levels of PER1, AKAP12 and MMP17 and metastasis in human ovarian serous tumors." (PMID 37434173, 2023).
tongue cancer (2 papers, 2016 to 2019). A malignant neoplasm affecting the tongue. "In nude mice subcutaneously injected with human tongue cancer cells, PER1 knockdown in the cells enhanced tumor development, leading to increased tumor weights and volumes." (PMID 31350984, 2019). "Of interest, the expression of key clock genes was either down-regulated, e.g., BMAL1, CLOCK, PER1, PER2, and PER3, or up-regulated, e.g. CYR1 and CRY2, in tongue cancer samples in relative to that in normal control samples." (PMID 27079271, 2016).
acne (1 paper, 2022). An inflammatory process of the sebaceous glands which is characterized by comedones, nodules, papules and/or pustules on the skin. "We found that Bmal1 and its target genes Rev-erbα, Dbp, Per1 and Cry2 were down-regulated in the skin of P. acnes-treated mice, suggesting a role of Bmal1 in the condition of acne." (PMID 35414779, 2022).
adenoma (1 paper, 2015). A neoplasm arising from the epithelium. "A statistically significant reduction in PER3 expression was observed in adenomas relative to normal tissue among each of the available data sets; similar differences were noted for PER1, and to a lesser extent PER2 expression." (PMID 25501848, 2015). "Data for PER1, PER2 and PER3 expression in adenomas relative to normal tissue were retrieved from the Oncomine microarray database." (PMID 25501848, 2015).
age (1 paper, 2018). A temporal measurement of the time period elapsed since an identifiable point in the life cycle of an organism. "Broadly, this work suggests that Per1 may be a mechanism contributing to age-related impairments in both long-term memory and circadian rhythmicity, depending on the structure." (PMID 30127461, 2018). "Epigenetic repression of Per1 may therefore represent an important interface between age-related impairments in both circadian rhythmicity and long-term memory formation." (PMID 30127461, 2018). "Abnormal HDAC3-mediated repression of Per1 in the aging brain is therefore a key event that could lead to age-related impairments in both long-term memory formation and circadian rhythmicity." (PMID 30127461, 2018).
Arrhythmia (1 paper, 2022). Any cardiac rhythm other than the normal sinus rhythm. "Moreover, even though Bmal1 shRNA injection with the NTW array did not cause complete arrhythmia (lacking steady rhythms) in the SCN slice, effects on Per1::luc emission rhythms are proposed to depend on the identity and percentage of pacemaker cells injected with Bmal1 shRNA." (PMID 35293154, 2022).
Azoospermia (1 paper, 2022). Absence of any measurable level of sperm,whereby spermatozoa cannot be observed even after centrifugation of the semen pellet. "Further bioinformatics mining revealed that related clock genes (PER1, PER2, CRY2, NR1D1 and NPAS2) were down-regulated in non-obstructive azoospermia patients." (PMID 35910569, 2022).
benign breast disease (1 paper, 2019). "Since plasma shows lower cfDNA concentrations compared to serum, we tested the methylation frequency of SPAG6, PER1, NKX2-6 and ITIH5 in a plasma cohort, consisting of women with a benign breast disease (n = 14) and invasive breast cancer (n = 111)." (PMID 31741713, 2019).
cannabis dependence (1 paper, 2022). Physical and psychological dependence on the drug cannabis. "HES7/PER1 on chromosome 17 may represent a meaningful risk factor in the development of cannabis dependence and its severity." (PMID 36135314, 2022).
chronic lymphocytic leukemia (1 paper, 2017). "For example, the circadian oscillation of gene expression is aberrant in leukemic cells, as BMAL1, PER1, and PER2 are down-regulated in patients with chronic lymphocytic leukemia." (PMID 28487473, 2017).
chronic obstructive pulmonary disease (1 paper, 2025). A chronic and progressive lung disorder characterized by the loss of elasticity of the bronchial tree and the air sacs, destruction of the air sacs wall, thickening of the bronchial wall, and mucous accumulation in the bronchial tree. "Imbalances in autophagy levels resulting from disrupted oscillations and the expression of clock genes such as PER1 and PER2 are implicated in the pathogenesis of chronic obstructive pulmonary disease (COPD)." (PMID 41234362, 2025).
clear cell ovarian adenocarcinoma (1 paper, 2021). "We further analyzed the Oncomine data and found low expression of PER1 in mucinous ovarian adenocarcinoma, clear cell ovarian adenocarcinoma, serous ovarian adenocarcinoma, ovarian endometrioid adenocarcinoma, and ovarian endometrioid cystadenocarcinoma compared with normal ovarian tissue." (PMID 34220965, 2021).
cognitive decline (1 paper, 2021). "This may lead during aging to a Per1-associated excessive accumulation of misfolded proteins, which may consequently result in higher neuronal vulnerability and cognitive decline, introducing a novel function for this clock gene within neuronal homeostasis." (PMID 34572962, 2021).
colon adenocarcinoma (1 paper, 2021). "Compared to normal skin, patients with skin cutaneous melanoma (SKCM) present significant down-regulation in the expression of BMAL1, CRY1, CRY2, PER1, PER2, and PER3, and higher expression of CLOCK, a similar pattern was also observed in patients with colon adenocarcinoma (COAD)." (PMID 34966277, 2021).
dementia (1 paper, 2023). Loss of intellectual abilities interfering with an individual's social and occupational functions. "Furthermore, a previous study showed that abnormal methylation in circadian genes such as CRY1 and PER1 leads to dementia symptoms." (PMID 37388929, 2023).
dermatitis (1 paper, 2021). An inflammatory process affecting the skin. "Ionizing radiation-induced dermatitis, which commonly occurs in patients undergoing radiation therapy for cancer, is also stronger when the clock is disrupted by either an environmental disruption that mimics rotating shiftwork or by genetic disruption of Per1/2." (PMID 34204077, 2021). "Interestingly, a recent study showed that hairless mice lacking the Per1/2 expression or were put on a rotating light exposure schedule showed increased evidence of dermatitis following IR treatment." (PMID 34204077, 2021).
Familial advanced sleep-phase syndrome (1 paper, 2011). "For example, polymorphisms in PER1 and PER3 are associated with advanced sleep phase, and a rare missense mutation in PER2 is linked to familial advanced sleep phase syndrome (FASPS)." (PMID 21533241, 2011).
glaucoma (1 paper, 2026). Increased pressure in the eyeball due to obstruction of the outflow of aqueous humor. "Glaucoma-induced phase shifts and amplitude alterations in the rhythmic expression of Per1, Per2, Nr1d1, and Bmal1 in the pituitary and adrenal gland, resulted in a temporal misalignment between the pituitary and adrenal rhythms." (PMID 42029480, 2026).
Headache (1 paper, 2016). Cephalgia, or pain sensed in various parts of the head, not confined to the area of distribution of any nerve. "Moreover, transcriptional alteration in individual genes like the pain receptor P2rx3 and the circadian clock gene Per1 are interesting findings in relation to NO-provoked headache." (PMID 27213950, 2016).
Hepatic steatosis (1 paper, 2023). Steatosis is a term used to denote lipid accumulation within hepatocytes. "While fed on HFD, Per1-deficient mice demonstrated an obvious decrease in hepatic steatosis, liver TG, and TC accumulation." (PMID 37209828, 2023).
hypogonadism (1 paper, 2025). A disorder characterized by decreased function of the gonads. "Overall, these data identify Per1 and Per2 as novel atrophy-inducing genes with direct implications for their roles in regulating limb muscle mass loss during hypogonadism." (PMID 40632504, 2025).
Infertility (1 paper, 2020). "The fertility of young Per1 and Per2 knockout mice does not differ from wild-type mice during mild-age, highlighting that Per1-Per2 absence impairs infertility only in aged mice." (PMID 32486326, 2020).
insulinoma (1 paper, 2023). "Circadian expression of clock genes (Clock, Bmal1, Per1,2,3, and Cry1,2) in pancreatic islets and INS1 rat insulinoma cells may indicate that circadian rhythms are generated within the b-cells." (PMID 36768693, 2023).
invasive breast carcinoma (1 paper, 2019). A carcinoma that infiltrates the breast parenchyma. "PER1 showed an 11% increase in sensitivity for invasive breast cancer detection (cut-off methylation 3.8%, 31% sensitivity, 82% specificity), compared to analysis of all samples." (PMID 31741713, 2019). "We initially assessed promoter methylation of SPAG6, PER1, NKX2-6 and ITIH5 in a serum cohort consisting of samples of women with benign disease (n = 34), DCIS (n = 27) and early invasive breast cancer (n = 42)." (PMID 31741713, 2019). "Adding PER1 or NKX2-6 to the two-gene panel increases sensitivity for DCIS detection to 70%, although decreases sensitivity for early invasive breast cancer (39% and 41%, respectively) detection." (PMID 31741713, 2019).
ischemia (1 paper, 2013). A hypoperfusion of the BLOOD through an organ or tissue caused by a PATHOLOGIC CONSTRICTION or obstruction of its BLOOD VESSELS, or an absence of BLOOD CIRCULATION. "The Per1 levels at 18 h and 24 h after ischemia were significantly lower than their sham-operated counterparts." (PMID 24204346, 2013). "Taken together, these results suggest that ischemia resulted in a phase-advance of Per1 expression." (PMID 24204346, 2013). "Per1 levels on the other hand were significantly affected by ischemia." (PMID 24204346, 2013).
liposarcoma (1 paper, 2018). A usually painless malignant tumor that arises from adipose tissue. "PER1 rs3027178 was associated with a reduced predisposition only in liposarcoma subgroup (32%)." (PMID 30518396, 2018). "Moreover, in liposarcoma subgroup PER1 rs3027178, a genetic variant with a synonymous functional effect, was associated with a reduced predisposition (per allele OR 0.68; 95% CI 0.47–0.98; P = 0.04)." (PMID 30518396, 2018). "Moreover, PER1 rs3027178 was found to be associated only with liposarcoma susceptibility." (PMID 30518396, 2018).